POTEG (POTE ankyrin domain family member G)
Synonyms: POTE-14; A26C2; POTE14; POTE14alpha; CT104.4; ACTBL1; POTE22
Tractability: PROTAC: ubiquitination databases record sites on it.
Gene: Protein-coding gene on chromosome 14 (19,402,486 to 19,434,341, reverse strand). Ensembl gene ENSG00000187537.
Genetic constraint (gnomAD): Loss-of-function variants: 1 observed, 13.71 expected, observed/expected ratio (o/e) 0.073, 90% interval 0.025 to 0.35. The synonymous counts are far from expectation, so gnomAD's model fits this gene poorly and the ratio says little. Missense variants: 20 observed, 172.11 expected, observed/expected ratio (o/e) 0.12, 90% interval 0.081 to 0.17. Synonymous variants: 4 observed, 44.54 expected, observed/expected ratio (o/e) 0.0898, 90% interval 0.043 to 0.21.
Homologues: Paralogues in human: POTEM (99% identical), POTEH (98% identical), POTEI (91% identical), POTEF (90% identical), POTEE (90% identical), POTEB3 (89% identical), POTEC (87% identical), POTED (87% identical), POTEJ (84% identical), POTEB (82% identical), POTEB2 (82% identical), POTEA (55% identical), and 2 more.
Diseases named in the same sentence as POTEG in open-access papers:
POTEG is named in the same sentence as 1 disease in open-access papers, as found by Europe PMC text mining. Sharing a sentence is not in itself a finding about the gene and the disease. The quoted sentences say what the papers report.
cancer (2 papers, 2015 to 2021). A tumor composed of atypical neoplastic, often pleomorphic cells that invade other tissues. "They found that POTE proteins correlated well with malignant progression and metastasis in a variety of tissues and that POTEG and /or POTEH are pivotal for cancer cells to grow and survive." (PMID 25860145, 2015).